CD68 (CD68 molecule)
Diseases named in the same sentence as CD68 in open-access papers (continued):
Sharing a sentence is not in itself a finding about the gene and the disease.
gastric cancer (continued). "We first explored the clinical value of the CD68 (TAMs marker) in gastric cancer tissues from patients with gastric cancer who had undergone 5-FU-based neoadjuvant chemotherapy and elucidated the correlation between the infiltration of TAMs and the resistance of gastric cancer to chemotherapy." (PMID 36151545, 2022). "However, the recent report suggests that an increased density of CD68+CD163+ macrophages in tumor tissues is in fact associated with up-regulated immune signaling and improved survival of patients with gastric cancer." (PMID 35525858, 2022). "Notably, a significant correlation was also found with the distribution of the TAMs marker CD68, in gastric carcinoma tissues." (PMID 33537086, 2021). "Similarly, using the fIHC method, higher infiltration with M2 macrophages (CD68+CD163+CD206+) in the stroma was found in gastric carcinoma, and, conversely, higher M1 populations were detected in a tumor-nest area." (PMID 33807310, 2021). "Moreover, the combined detection of CD68 and Sema4D protein markers was shown to have a potential for predicting gastric carcinoma progression and prospective patient prognosis." (PMID 33537086, 2021). "Although our data suggest that IL-34 and CD68+ TAM might be useful biomarkers in gastric cancer, other factors, for example, Epstein–Barr virus infection, are well known to be linked with gastric cancer." (PMID 32765828, 2020). "Interestingly, the expression levels of CD8 and CD68 were reversed during the progressive stages of gastric cancer." (PMID 30813210, 2019). "Three cases of gastric cancer were examined for CD68 and CD163 expression in the tumor stroma." (PMID 31413815, 2019). "Moreover, CD68 + macrophages were upregulated at the SARIFAs in our study of gastric cancer." (PMID 38926671, 2024). "In patients with gastric cancer, expression levels of CD68+ TAMs and TLSs are negatively correlated; high expression of CD68+ TAMs usually indicates low expression of TLSs, suggesting an association between TAM presence, gastric cancer progression, and lower survival rates." (PMID 39840050, 2024). "This study was performed to investigate programmed cell death protein 1/programmed death ligand 1 (PD1/PDL1) expression and their correlations with CD8+ T cell/CD68+ macrophage (CD68+ M) densities in gastric cancer (GC) at different microsatellite statuses." (PMID 33613757, 2021). "In the stomach, along with the diminishing of AKR1B10 expression, CD68+ macrophage increased and CD19+ B cell decreased in gastric cancer." (PMID 39712017, 2024). "In the study of gastric cancer, the researchers found that CD68+IRF8+M1 TAMs and CD68+CD206+M2 TAMs were closest to the tumor cells, while CD68+CD163+CD206+M2 TAMs were farthest from the tumor cells." (PMID 38279145, 2024). "However, in gastric cancer, CD68 was shown not to be associated with poor prognosis." (PMID 38189834, 2024). "We assayed the protein expression of YKL-39, CD68, and CD34 by immunohistochemistry in tissues of 119 patients with gastric cancer, as well as the intracellular expression of YKL-39 and CD68 by immunofluorescence." (PMID 36372883, 2022). "Data were analyzed with SPSS Statistics 25.0 to explore the impact of expression of YKL-39, CD68, and CD34 in gastric cancer patients and the relationship among them." (PMID 36372883, 2022). "In three cancer types (i.e., anaplastic thyroid, colorectal, and gastric cancers), mIF consistently illustrated the proximity of some SPP1+ TAMs (SPP1+CD68+) to CAFEndMT (CD44+CD31+)." (PMID 36333338, 2022). "We found that the ratio of CD169+ to CD68+ cells was positively correlated to the density of CD8+ TILs in both total and advanced gastric cancer (total; R = 0.367, p < 0.001; advanced; R = 0.317, p < 0.001)." (PMID 33816277, 2021). "NACT in gastric cancer induced CD3+ and CD8+ T lymphocytes as well as CD68+ and CD163+ macrophages in the tumor microenvironment in combination with its direct cytotoxic effects." (PMID 34697289, 2021).
gastric cancer (continued). "Immunohistochemistry for CD68 and CD169 was performed using RLN specimens, and that for CD8 was done using primary cancer specimens in 294 gastric cancer cases." (PMID 33816277, 2021). "Subgroup Cox regression analysis in patients with esophageal cancer showed that high infiltration of CD68+ macrophages was prognostic in the unadjusted model whereas high infiltration of both CD68+ and CD163+ macrophages were prognostic in gastric cancer." (PMID 33194593, 2020). "We classified the gastric cancer cases into 4 groups based on their CD8+ TIL and CD68+ TAM statuses." (PMID 31521128, 2019). "In this study, we enrolled 112 gastric cancer patients, immunofluorescence was used to evaluate the colocalization of CD3, CD4, CD56, CD20, CD68, and mast cell tryptase (MCT) with IL-17." (PMID 25197971, 2014). "Two TMA slides, each containing 90 pairs of gastric cancer and corresponding paracancerous tissues, were selected for mIF analysis of TOB1, CD8, CD4, FOXP3, CD20, CD68, and CD66b to investigate the profiles of TOB1 protein expression and immune cell infiltration in gastric cancer." (PMID 38617839, 2024). "In addition, the CCL14 protein in the TILs of gastric cancer tissues was related to Lauren’s type cells, T cells (CD4+ and CD8+), and CD68+ macrophages in the TME." (PMID 38887558, 2024). "This study verified AKR1B10 expression and immune infiltration in gastric cancer, and our results consistently demonstrated that AKR1B10 expression was diminished in gastric cancer accompanied with CD19+ B cell proportion decline and CD68+ macrophage increase." (PMID 39712017, 2024). "Western gastric cancers generally have high levels of T cell markers (CD3, CD45R0, CD8) and low numbers of regulatory T cells, and low levels of inflammatory cell markers (CD66b, CD68) compared to Asian gastric cancers." (PMID 37048719, 2023). "The immune cell compartment of HER2/PD-L1 positive gastric cancer shows the highest infiltration of CD68-positive immune markers versus negative compartments." (PMID 34944780, 2021). "Altogether, these results suggest that gastric cancer patients with a CD8+ TIL-positive and CD68+ TAM-negative status (defined as type I above) might benefit more from PAC." (PMID 31521128, 2019). "The density of CD68+ or CD163+ TAMs in four different areas (epithelial and stromal compartments of both the tumor center and invasive front) were analyzed in 143 cases of MSI-high advanced gastric cancers using a computerized image analysis system." (PMID 26714314, 2015). "A possible reason for the similar effect of CD68+ macrophages and cTOB1+CD68+ macrophages on gastric cancer patient survival is that cTOB1 may not exert an anti-proliferative function." (PMID 38617839, 2024). "For instance, in gastric cancer, an analysis of tissues from 56 human cases through multiplex immunohistochemistry (mIHC) identified seven distinct TAM populations based on CD68, CD206, and CD163 expressions, uncovering that not all M2 macrophages directly influence tumor progression." (PMID 39068459, 2024). "However, this simplified dichotomy may not hold for all primary tumor sites, as high CD68+ TAM density has been identified as a negative prognostic indicator in breast and gastric cancer." (PMID 33882057, 2021).
lung carcinoma (56 papers, 2011 to 2025). "As expected, BrM tumors exhibited significantly less infiltration of CD3+ immune cells but abundantly more CD68+ tumor-associated macrophages compared to primary lung cancers." (PMID 39593114, 2024). "Researchers detected the expression of Tim-3 in tumor-associated macrophages in lung cancer tissues, and in CD68+ tumor-associated macrophages, lung cancer patients with high Tim-3 expression had shorter OS and poorer prognosis." (PMID 36439090, 2022). "As for the micro-distribution of TAMs and survival, low density of CD68+ TAMs and CD68+HLA-DR+ M1 TAMs in lung cancer islet were both associated with poor OS, while islet CD68+CD163+ M2 TAM density was not correlated with prognosis." (PMID 27144518, 2016). "The over-expression of TAMs-specific CD68 around lung tumor tissues was detected and associated with lung cancer progression." (PMID 23227270, 2012). "Association between CD68 expression in adjacent tumor tissue and clinical characteristics of lung cancer (n = 67)." (PMID 23227270, 2012). "We also identified a population of CD68 weakly positive (CD68dim) cells in the lung cancer tissues that being associated with improved responses, which may be insightful for future studies of tumor immunity." (PMID 38898200, 2024). "Moreover, the accumulation of CD163+ macrophages is closely correlated with a poor prognosis in lung cancer, and the increased density of CD68+CD163+ macrophages in tumor nests and stroma was associated with lymph node metastases." (PMID 36077342, 2022). "Furthermore, the number of CD68-positive cells in the lung cancer tissues was closely associated with the pathological type and tumor cell differentiation (p < 0.05)." (PMID 25823926, 2015). "Serial section staining of IL7R and CD68 in colon-, stomach-, and lung cancers confirmed strong expression of IL7R in the macrophage compartment." (PMID 38424167, 2024). "In CRC and lung cancer we also observed high expression of APOE, encoding Apolipoprotein E, restricted to CD68+CD163+ macrophages." (PMID 36724681, 2023). "Immunohistochemical analysis of human lung cancer specimens obtained from the two different groups of patients revealed that high CD68 expression levels in the peritumoral space correlated with strong positivity for IL-1β in patients with a poor prognosis." (PMID 35884397, 2022). "Accordingly, we evaluated CD68 and IL-1β scores in histological lung cancer specimens from early NSCLC patients with poor survival and long survival." (PMID 35884397, 2022). "This is supported by our findings showing that AIF-1 expression was significantly, positively correlated with CD68 expression in lung cancer and co-localized with CD68+ macrophages." (PMID 36520870, 2022). "Encouragingly, we also found this TUBB3+CD68 TAM subset in a 10× scRNA-seq dataset of human non–small cell lung cancer (NSCLC) biopsy with strong expression of neuronal genes including BMP7, SHANK, CHL1, and PAX6." (PMID 36206343, 2022). "This is similar to prior reports where in vitro differentiation to dendritic cells by GM-CSF/IL-4 was inhibited by soluble factors secreted by lung cancer cells, and suggests that monocyte differentiation in tumors is skewed towards CD68+ macrophages." (PMID 33069212, 2020). "Immunohistochemical staining of lung cancer specimens with an anti-FROUNT antibody showed that FROUNT is expressed in stromal cells, and highly expressed by CD68+ tumor-associated macrophages in particular." (PMID 32001710, 2020). "In peripheral blood collected from patients with lung carcinoma, B7-H4-expressing CD68+ macrophages were found." (PMID 33194645, 2020). "Substantial infiltration of CD45+ hematopoietic cells and CD68+ macrophages/microglia was further detected in patient BrM originating from breast and lung cancer by immunofluorescence." (PMID 31501884, 2020). "Lung cancers with increased FoxP3+ T regulatory cells or increased MCs had worse OS, and cancers with increased CD68+ macrophages had worse DFS." (PMID 31903172, 2019).
lung carcinoma (continued). "Our study shows that elevated CD68+ TAMs in tumor islet are correlated with better OS of lung cancer." (PMID 27248173, 2016). "In the lung tumor tissues, IL10 accumulated in the epithelial cells and CD68+ macrophages, suggesting that IL10 from cancer cells and tumor-associated macrophages is involved in lung cancer progression." (PMID 26956044, 2016). "Another study used the protein named triggering receptor expressed on myeloid cells-1 (TREM-1) as a marker for TAMs and reported that TREM-1 was expressed only by CD68+ TAMs in lung cancer tissue." (PMID 27144518, 2016). "By double IHC, the detection of 20.1% of CD68+CD163- AMs among CD68+CD163+ AMs in lung tissue adjacent to the cancer margin suggested that AMs in lung tissue adjacent to lung cancer were mostly composed of M2 macrophages." (PMID 26900851, 2016). "By IHC assay, we found that Cd68 positive macrophages were also strongly stained by Spp1, whereas Ttf1-positive lung cancer cells were only weakly stained positive for Spp1." (PMID 26565418, 2015). "By IHC assay, we found that both the Ttf1-positive lung cancer cells and Cd68-positive macrophages were stained positive for Cxcl13, but Ttf1-positive cells constituted more than 95% of the cellular component of the lung tumor tissues of the mice." (PMID 26565418, 2015). "The number of CD68-positive cells in the lung cancer tissues was 119.56 ± 5.35, which was significantly higher than that in the adjacent normal lung cancer tissues (26.75 ± 10.38; n = 57, p < 0.05)." (PMID 25823926, 2015). "The expression of TAMs-specific CD68 in lung cancer tissues and paired adjacent tissues from cancer patients was determined using immunostaining." (PMID 23227270, 2012). "The correlation was studied between CD68 high expression in adjacent lung cancer tissue and clinicopathologic characteristics of lung cancer including age, gender, differentiation of tumor cell, metastasis to lymph node, TNM stage and tumor invasion to pleura." (PMID 23227270, 2012). "In this study, we observed that the expression levels of CD68+ TAMs were increased in adjacent lung tumor tissue and correlated with lung cancer progression and metastasis, which was consistent with these observations." (PMID 23227270, 2012). "For example, increases in tumor islet CD68+ macrophage density and the tumor islet and/or stromal macrophage ratio were significant independent predictors of increased survival in patients with surgically resected non–small cell lung cancer." (PMID 36968220, 2023). "MPE-Mφ collected from lung cancer patients were identified as CD14+ CD68+ macrophages." (PMID 33175182, 2021). "However, there are still some reports in Chinese cohorts where the correlation of CD68+ cells with clinical parameters of lung cancer was examined." (PMID 33194645, 2020). "A positive correlation between HIF1A and CD68 in colon cancer patients was identified but, unexpectedly, in cases with higher macrophage infiltration, HIF1A expression was associated with a better prognosis, in contrast to breast, gastric, and lung cancers." (PMID 32231135, 2020). "The lung carcinoma lesions were positively correlated with lung tissue injury and macrophage infiltration in alveolar cavities in the control group, these macrophages showed mainly a M1-like (iNOS+/CD68+) phenotype." (PMID 30984004, 2019). "However, the results from studies evaluating the correlation between TAMs and survival of lung cancer using CD68 as a marker of TAMs are still contradictory." (PMID 27248173, 2016). "In contrast, elevated CD68+ TAMs in tumor stroma are correlated with worse OS of lung cancer." (PMID 27248173, 2016). "Notably, immunofluorescent staining detected SIRT2 proteins either barely overlay with ITGB3‐aK416 positive lung cancer cells or sporadically overlay with CD68 positive macrophages, indicating SIRT2 proteins visualized here were mainly distributed in the extracellular space." (PMID 36453571, 2023).
lung carcinoma (continued). "At five weeks, prior to lung carcinoma lesions, the four urethane injections led to obvious lung injury in control group, presenting as an increase in lung inflammation and injury area, which were positively correlated with macrophage infiltration (CD68+ cells)." (PMID 30984004, 2019). "We further found that the expression of TSG6, CD44, CD68, and CD163 (marker of TAMs) is elevated in metastatic lung cancer tissues of mice driven by active PLK1." (PMID 40860188, 2025). "Forced MALAT1 expression led to enhanced growth and invasiveness of lung cancer cells, both in vitro and in vivo, accompanied by elevated levels of MCP-1, CD68, CD163, CD206, and KI67." (PMID 38791954, 2024). "Here we observe a rise in MALAT1 expression, correlating with increased levels of MCP-1 and CD68, CD163, CD206, indicative of M2 macrophages in tumor tissues of AA lung cancer patents." (PMID 38791954, 2024). "We also found that in lung cancer patients receiving neoadjuvant immunotherapy, more infiltrated CD3+, CD4+, CD8+, or CD68+ cells were detected in pre-treatment tumor tissues from patients achieving pathologic complete response (pCR)." (PMID 38762546, 2024). "Our results from the NSCLC discovery cohort were validated by single-cell sequencing of three lung carcinomas where LAIR-1 was highly expressed on CK8/CK10+ tumor cells and CD68+ and CD163+ macrophages." (PMID 36960400, 2023). "To deconvolute the TIME in lung cancer patients with COPD, we investigated PD-1, PD-L1, CD8 T lymphocytes, and CD68 macrophage in the stroma and tumor areas." (PMID 37388220, 2023). "Our study revealed different genetic aberrations and pathways, higher neoantigen burden, and higher level of CD68+ macrophages and CD8+ T lymphocytes in lung cancer patients with COPD." (PMID 37388220, 2023). "Our study suggests different genetic alterations, pathways, higher neoantigen burden and the presence of higher density of CD68+ macrophages and CD8+ T lymphocytes in lung cancer patients with COPD." (PMID 37388220, 2023). "Our findings are in line with a previous study on non‐small cell lung cancer (NSCLC), investigating both human tumor tissues and cancer cell lines, indicating that high expression of CD47 and CD68 promotes tumor invasion and metastasis." (PMID 36598153, 2023). "In support of this, the TCGA-based analysis revealed that the levels of human macrophage marker CD68 and TLR4 were negatively correlated with the overall survival of patients with lung cancer." (PMID 36542153, 2022). "Nevertheless, the same MRT geometry for liver and shown previously was still recognizable by both the DNA damage biomarker γH2AX at 48 h post-irradiation and the pan-macrophage biomarker, CD68, at 7 days post-MRT in irradiated lung carcinoma." (PMID 35453485, 2022). "Immunostaining analysis of human lung cancer tissue revealed that MafB is expressed in the same region and mostly in severe samples together with CD204+ and CD68+ TAMs." (PMID 33194645, 2020). "In human lung cancer samples from 72 NSCLC patients, intratumor CD68+ TAM infiltration and CCR2 expression correlated with tumor stage and metastasis." (PMID 33194645, 2020). "Both CD68+ TAM density and micro-distribution (islet and/or stroma) in lung cancer tissues were studied." (PMID 27144518, 2016). "Opposite survival effects of CD68+ TAM infiltration in the tumor islet and stroma were observed in lung cancer patients." (PMID 27144518, 2016). "We investigated which cells were involved in BaP-induced lung cancer by analyzing cell surface markers in the tumor microenvironment using antibodies against CD45, CD19, CD4, and CD68." (PMID 26565418, 2015). "Moreover, the immunofluorescence results showed a clear and abundant population of cells co-expressing CD68 and TREM2 in human lung cancer than that in healthy lung." (PMID 39135069, 2024).